CD4 (CD4 molecule)
Diseases named in the same sentence as CD4 in open-access papers (continued):
Sharing a sentence is not in itself a finding about the gene and the disease.
breast cancer (continued). "To this end, we obtained FFPE tumor tissue from the same breast cancer patients assessed before for TCR clonality in PB and performed Immunofluorescence analysis on serial tissue sections against CD4, FOXP3, and CD127." (PMID 33602930, 2021). "Overall, we found that lower expression level of ACE2 was related to poorer prognosis of breast cancer in enriched CD8+ T cells (p=0.04), enriched CD4+ T cells (p=0.04) and enriched dendritic cells (p=0.04)." (PMID 34413267, 2021). "CXCL13 is enriched in fibroblasts and CD8 + T cells in breast cancer, CD8 + Tex and CD4 + Tconv cells in colon cancer, and plasma in pancreatic cancer." (PMID 34439306, 2021). "A positive influence of NSAR intake was described on the number of tumor-infiltrated CD4 and CD8 T cells in a mouse model of breast cancer and on reducing proliferation of suppressive myeloid cells." (PMID 35008239, 2021). "The IHC staining with anti-CD68, anti-CD4, and anti-CD8 detected CD68+ macrophages, CD4+, and CD8+ T cells, respectively, in rat mammary tumors." (PMID 34164110, 2021). "However, we found that octogenarians’ breast cancer had a significantly higher infiltration of pro-cancer immune cells, M2 macrophage, and regulatory T cells and a lower infiltration of anti-cancer immune cells, M1 macrophage, and activated memory CD4 T cells compared to younger controls." (PMID 34208219, 2021). "Specifically, in breast cancer (BC) models, upregulation of lnc-SNHG1 in CD4+ TILs promotes their differentiation into Tregs by interacting with miR-448, a negative regulator of indoleamine 2,3-dioxygenase (IDO)." (PMID 34943820, 2021). "We found that CD177+ or CD177− TI Treg cells, defined as CD4+CD25+CD127low, from human cancer specimens exhibited a similar level of FOXP3 protein in 1 breast cancer, 2 colon cancers and 3 ccRCCs." (PMID 34599187, 2021). "CD4+ T cells, CD8+ T cells, and CD20+ B cells are more abundant in all breast cancer subtypes compared to normal breast tissue." (PMID 33467084, 2021). "In breast cancer, CD8+ T cells, CD4+ T cells, M0 and M2 macrophages showed lower infiltrating concentration in the high tumor-associated immune genes groups, which suggested an adverse association between them." (PMID 33763366, 2021). "In this important context, the combination of a high density of TAMs and low infiltration of CD4+, CD8+ T TILs in human breast cancer is indicative of poorer survival." (PMID 34089486, 2021). "Immunohistochemistry was used to detect tumour-infiltrating CD20+ (B), CD4+ (helper T), CD8+ (cytotoxic T) and FoxP3+ (regulatory T) cells in breast cancers from 62 patients, with quantification in tumour stroma, tumour cell nests, and tumour margins." (PMID 32577938, 2020). "In the studied cohort of patients with early HR+ breast cancer, tumour-infiltrating CD20+ B-cell, CD4+ T-helper-cell and CD45RO+ memory T-cell densities were significantly associated with DFS." (PMID 33153211, 2020). "CD4+ CD25+ FoxP3+ Treg cells are a major immunosuppressive cell and, while they prevent deleterious autoimmune diseases, their presence in the breast cancer TME are a significant hurdle for effective BC vaccine responses." (PMID 32937885, 2020). "Previous studies on TILs in breast cancer identified lymphocyte populations that were mainly comprised of CD8+ cytotoxic T cells and CD4+ regulatory cells together with varying proportion of other helper T cells, B cells and NK cells." (PMID 32410705, 2020). "In this study, 4T1 breast cancer cells were transplanted into BALB/c mice, and the homogeneity and heterogeneity of CD4+CD25+ T cells TCR β CDR3 repertoires in breast tumor tissues, lung metastatic tissues, and spleens were monitored by the HTS technique." (PMID 33029539, 2020). "In breast cancer, TILs are largely composed of CD8, and to a lesser extent, CD4 T cells, regulatory T cells, macrophages, mast cells, and plasma cells." (PMID 32971948, 2020).
breast cancer (continued). "Previous studies have confirmed that the number and proportion of CD4+CD25+Tregs subsets are related to the pathological type, metastasis, and prognosis of breast cancer closely." (PMID 33029539, 2020). "We also analyzed the correlation of immune cells in ACE2 function such as CD4+, CD8+ and B cells in breast cancer subtypes." (PMID 33178900, 2020). "Fluorescent multiplex immunohistochemistry (mIHC) was used to stain CD4, CD8, PD1, TIM3, and cytokeratins simultaneously in paired breast cancer samples before and after neoadjuvant therapies (NAT) in a prospective cohort (n = 50)." (PMID 32894006, 2020). "Collectively, we found that breast cancer cells upregulated the expression of PD-1, CTLA-4, TIM-3 and LAG-3 in the different subsets of CD4+ T cells." (PMID 31614877, 2019). "In breast cancer patients, analysis of bone marrow detected both TCM and TEM phenotype CD4+ T cells, and the adoptive transfer of these cells into NOD scid mice with patient tumor transplants showed infiltration of these cells into the tumors." (PMID 31379821, 2019). "In luminal breast cancer, JAK1 expression levels were positively correlated with infiltrating levels of CD8+ T cells, CD4+ T cells, macrophages, neutrophils, and dendritic cells." (PMID 31790361, 2019). "In basal-like breast cancer, JAK1 expression levels were positively correlated with infiltrating levels of CD4+ T cells, neutrophils, and dendritic cells." (PMID 31790361, 2019). "This pro-tumoral CXCL10 feed-forward loop was also observed in breast cancer; albeit, CXCL10 also attracted more CD4+ and CD8+ lymphocytes to the TME, in a paracrine manner, which attenuated tumor progression." (PMID 31216755, 2019). "As such, double positive CD4 and CD8 T cells have been described in both healthy donors, patients with inflammatory disorders and patients with cancer, including breast cancer." (PMID 31417550, 2019). "In the mouse breast cancer model, CD19+B220+CD25+ B cells inhibit T cell production by producing TGF-β and contact with cells and induce the transformation of young CD4+ T cells to FoxP3+ Tregs." (PMID 31662750, 2019). "Our previous study showed that CD4+ and CD8+ T lymphocytes play crucial roles in breast cancer progression and outcome." (PMID 30728051, 2019). "Similar to clinical breast cancers and consistent with previous reports of triple‐negative breast cancer growth in HIS mice, CD4+ T cells were the major infiltrating TIL subpopulation, with CD8+ T cells accounting for ~ 20–30%." (PMID 30120895, 2018). "Furthermore, in patients with breast cancer, a limited bioinformatics analysis shows that patient outcome (metastases-free survival) is associated with an inverse pattern of metabolism-related (LDH-A and HIF-1α) and immune-associated (CD3E and CD8A, CD4) gene expression." (PMID 30248111, 2018). "Here for the first time we demonstrate that the deletion of a2V in the HSC leads to a significant reduction of CD4+ and CD8+ T cells in the periphery, which in turn, promotes breast cancer growth and metastasis." (PMID 30237863, 2018). "In a mouse model of human breast cancer, the depletion of CD4+CD25+ T cells was shown to reduce CD4+CD25+ T cell-mediated suppression, improve immunity, and enhance tumor regression." (PMID 28669079, 2018). "In breast cancer tissue, CXCL13+ CD4+ T cells accumulate either within small B cell aggregates, adjacent to B cell follicles, or occasionally within B cell follicles." (PMID 30190721, 2018). "In the present study, we showed that HER2 specific CD4+ Th1-cells, when encountering antigen, induce senescence and apoptosis in HER2-expressing breast cancer cells." (PMID 29796172, 2018). "In women with breast cancer, positive correlations were found between anti CMV IgG levels and percentage of CD4+CD27−CD28− (rs = 0.71, p < 0.0001), CD8+CD27−CD28− (rs = 0.44, p = 0.04), NK-T cells (rs = 0.51, p = 0.02), and NK cells (rs = 0.56, p = 0.007)." (PMID 30061900, 2018).
breast cancer (continued). "Interestingly we have also noted a similar loss in anti-HER3 CD4+ Th1 in TNBC and ERpos breast cancer suggesting similar loses of anti-oncodriver Th1 may be a common theme in several breast cancer subtypes and replacing Th1 cytokines may be a critical component in breast cancer therapy in general." (PMID 29796172, 2018). "The levels of intra-tumoural TILs, CD4+ and CD8+ T cell subsets in ALN metastatic tumour deposits were comparable with the levels in the corresponding primary breast cancers." (PMID 29390966, 2018). "We investigated the clinical significance of CD4, forkhead box P3 (FOXP3), and B cell attracting chemokine leukocyte chemoattractant-ligand (C-X-C motif) 13 (CXCL13) in early breast cancer." (PMID 29482642, 2018). "We first compared Treg frequencies by flow cytometry in PB and BM of healthy individuals (PB n = 7 and BM n = 8) and 50 breast cancer patients using CD25, FoxP3, and CD4 as Treg markers." (PMID 28224210, 2017). "We assessed CD74 and MHCII expression in tumor cells, as well as CD8, CD4, and CD68 tumor infiltrating leucocyte (TIL) density by immunohistochemistry in a cohort of 492 breast cancer patients." (PMID 27058619, 2017). "Immunohistochemistry was performed to determine PD-L1 tumor cell expression and to enumerate CD8, CD4 and CD68 tumor-infiltrating leucocytes (TIL) in a cohort of 443 breast cancers categorized by molecular subtype." (PMID 28881675, 2017). "In other cancer types such as breast cancer and NSCLC, TIL-Bs can act as antigen presenting cells (APCs) for a variety of tumor antigens and interplay with CD4+ and CD8+ T cells for increased survival." (PMID 27738332, 2016). "CD3 T cell level, CD4 T cell level, CD8 T cell level, and CD4/CD8 ratio are used as measurements for the evaluation of immunoregulation in breast cancer patients." (PMID 27239216, 2016). "Our results suggested that both CD4+ and CD8+ T cells are dynamically involved in the immune responses in breast cancer." (PMID 25968569, 2015). "We also analyzed CD4+ and CD8+ T cell infiltration in primary breast cancer tissues from cancer patients." (PMID 25968569, 2015). "We found that lymph node status, tumor stage, tumor-infiltrating CD4+ and CD8+ T cell numbers, and CD4/CD8 ratio were all significant factors for the prediction of breast cancer outcomes." (PMID 25968569, 2015). "Given that immune system has duel roles of tumor surveillance and promotion during the tumor development, we investigated clinical significance of CD4+ and CD8+ T cells in human breast cancer." (PMID 25968569, 2015). "T-cell responses to Her-2 peptide pools in vitro were assessed by analyzing pro- and anti-inflammatory cytokine production by CD4+ and CD8+ T-cells in 40 elderly and 35 younger breast cancer patients." (PMID 26500775, 2015). "Collectively, both CD4+ and CD8+ T cells were accumulated in the tumor microenvironment but with different increased trends during breast cancer development and progression." (PMID 25968569, 2015). "To better understand the roles of CD4+ and CD8+ T cells in the pathogenesis of breast cancer, we utilized 4T1 and E0771, two distinct mouse breast cancer models to mimic different clinical stages of human breast cancer." (PMID 25968569, 2015). "In the current study, we investigated CD4+ T cell subsets and CD8+ T cells in tumor sites and other multiple organs during the course of tumor development and progression in two breast cancer models." (PMID 25968569, 2015). "Considering the results presented in this study, depletion of Her-2-specific IL-5- and IL-17-producing CD4+ T-cells and enrichment of TNF-producing CD8+ T-cells for adoptive T-cell therapy would be important in breast cancer." (PMID 26500775, 2015). "Here we utilized two murine breast cancer models (4T1 and E0771) and demonstrated that both CD4+ and CD8+ T cells were increased and involved in immune responses, but with distinct dynamic trends in breast cancer development." (PMID 25968569, 2015).
breast cancer (continued). "Taken together, our results clearly indicate that CD4+ and CD8+ T cells have distinctly different roles in controlling breast cancer progression and outcomes." (PMID 25968569, 2015). "In order to further elucidate the functional properties of monocytes from breast cancer patients, freshly isolated monocytes were co-cultured with CD3/CD28 activated naïve CD4+ T cells in an allogeneic T cell suppression assay." (PMID 25992611, 2015). "Our results indicated that the CD4+/CD8+ ratio was significantly different in the peripheral blood, the tumor tissues, and the dLN in patients with breast cancer." (PMID 25605488, 2015). "In contrast, significantly increased numbers of both CD4+ and CD8+ T cells were detected in breast tumor tissues, which were consistent with the findings in mouse breast cancer models." (PMID 25968569, 2015). "Analysis of percentage distribution showed a predominant CD4 subpopulation over CD8 and CD20 in untreated breast cancer." (PMID 25432519, 2014). "We analyzed pre- and post-treatment tumor-infiltrating immune cells (CD3, CD4, CD8, CD20, CD68, Foxp3) by immunohistochemistry in a series of 121 breast cancer patients homogeneously treated with neoadjuvant chemotherapy." (PMID 25432519, 2014). "The most commonly tested markers for TILs subset tested in breast cancer are CD3+, CD4+, CD8+ and FOXP3+." (PMID 25501357, 2014). "Eleven studies evaluated the effects of MBTs on CD4 in a total of 676 participants with diseases (HIV, breast cancer, and ulcerative colitis) and 101 healthy individuals." (PMID 24988414, 2014). "TILs subset in breast cancer, primarily CD3+, CD4+, CD8 and (regulatory T-lymphocytes expressing forkhead box P 3 protein) FOXP3+ lymphocytes, have also been studied in the relationship of the pCR rate." (PMID 25501357, 2014). "Previous studies have revealed that the CD4+/CD8+ ratio for lymphocytes of peripheral blood and peritoneal fluid seems helpful in monitoring disease progression in ovarian or breast cancer patients." (PMID 23349693, 2013). "Using a mouse model of breast cancer,we show that RANKL production by tumor-primed CD4+ T cells is requiredfor development of bone metastasis." (PMID 23935856, 2013). "It was previously shown that in the murine mammary carcinoma model, deletion of Tregs resulted in increasing numbers of IFN-γ and IL-2-producing CD4+ T cells at tumor sites." (PMID 22890822, 2013). "Specifically in breast carcinoma, the number of FOXP3 CD4+CD25+ Treg and decreased ratios of CD8 T cells/FOXP3 Treg are correlated with a poor prognosis." (PMID 23861693, 2013). "IFN-γ production was found to be significantly reduced in the CD4+CD44+ T cell compartment in Il27ra−/− compared to Il27ra+/+ mice in both the fibrosarcoma and mammary carcinoma models." (PMID 23554861, 2013). "For example, CD4+ and CD8+ T-cells isolated from breast cancer patients are less responsive to IL-7, as measured by STAT-5 phosphorylation." (PMID 21920046, 2011). "CD28 expression was studied in CD4+ and CD8+ T-lymphocyte subsets and compared with CD3-ζ expression in sentinel node biopsies from breast cancer patients." (PMID 15613231, 2004). "In patients with HER2 + breast cancer, elevated levels of anti-HER2 CD4 + T-bet + IFN-γ + Th1 cells correlate with pathologic responses following neoadjuvant trastuzumab and chemotherapy, and they are associated with a reduced risk of recurrence and improved prognosis." (PMID 41582199, 2026). "CD4+ and CD8+ cell levels in AT3 breast tumors of infected and uninfected mice were compared by flow cytometry, and the results showed that Fn reduced CD4+ and CD8+ cells and promoted breast cancer growth and metastasis." (PMID 41011774, 2025).
breast cancer (continued). "We investigated whether the ability of calcipotriol to suppress PyMt mammary tumor growth relied on TSLP and CD4+ T cells." (PMID 39782693, 2025). "The relationship with undifferentiated M0 macrophages and negative correlation with CD4+ non‐regulatory T cells points to a complex immunomodulatory role for LARP6 in shaping the breast cancer microenvironment that warrants further mechanistic studies." (PMID 40635123, 2025). "To determine the impact of irradiation on the tumor immune infiltrate in Brca1co/coMMTV-Cre mammary tumors, we isolated single cell suspensions from tumor tissues and conducted flow cytometry analysis of CD45+ leukocytes stained for CD11b, Gr 1, F4/80, CD4, CD8α, and PD-1." (PMID 41208884, 2025). "In mouse models of breast cancer, S100A4 promotes the recruitment of pro-tumor Th2 polarized CD4 T cells to both the primary tumor and metastatic sites to promote disease progression, and antibody blockade of S100A4 reduces CD3+ T cell infiltration in the primary tumor and lung metastasis." (PMID 40078995, 2025). "CD8+ T cells are primarily involved in tumor killing and improved prognosis, whereas intra-tumoral CD4+ T cells have negative prognostic effects on breast cancer patient outcomes." (PMID 40141437, 2025). "In breast cancer, MHC‐II+ tumour cells in tumour‐draining lymph nodes (TDLNs) were found to lack costimulatory signals, thereby promoting regulatory T cell (Treg) expansion and suppressing CD4+ effector responses, ultimately facilitating lymph node metastasis." (PMID 40673641, 2025). "An ER+ breast cancer model is supported by evidence of increased myeloid inflammatory activity, less metabolically active endothelium, attenuated cancer cell IFN responses, and CD4+/CD8+ T cell quiescence and metabolic dysfunction with age." (PMID 41188599, 2025). "Notably, in patients with breast cancer, CD117+ granulocytes correlate with cancer status, and CD45RO+ CD4+ memory T‐cell counts rise after adjuvant radiotherapy." (PMID 39749673, 2025). "The observed increase in macrophage phagocytosis and tumor-infiltrating CD4+ and CD8+ cells in breast cancer cells suggests that altering macrophage clock gene expression via MCS could enhance the antitumor activity of immune cells against breast cancer." (PMID 39744689, 2025). "In our study, we identified a significant inverse correlation between the expression of BAP31 and the infiltration levels of various immune cells, such as myeloid-derived suppressor cells, macrophages, CD4+ T cells, CD8+ T cells, B cells, and neutrophils, in breast cancer." (PMID 40649753, 2025). "To test the effect of CD4+ Th2 cell immunity in late-stage breast cancer, we used a cell line derived from a MMTV-PyMttg mouse mammary tumor (the PyMt cell line) to establish mammary tumors in mice that represent late-stage breast cancer." (PMID 39782693, 2025). "Their results showed that Amy-F NPs could downregulate CD4 expression, synergize with the CD8-mediated suppression of CD80, and activate NKG2D expression in human breast cancer cells." (PMID 40303301, 2025). "In breast cancer, small molecules such as pristane and its derivatives target the malonyl/acetyltransferase domain of fatty acid synthase (FASN), disrupting fatty acid‐mediated MHC‐II silencing and thereby promoting CD4+ T cell infiltration." (PMID 40673641, 2025). "Additionally, C5a-C5aR signaling facilitates lung metastasis, a common occurrence in breast cancer, by suppressing the responses of CD8+ and CD4+ T cells and promoting the generation of regulatory T cells (Tregs) in situ." (PMID 40370471, 2025). "Our findings are inconsistent with two studies of breast cancer survivors where CD4+ T cells were lower in fatigued compared to matched nonfatigued survivors." (PMID 40709591, 2025).